PRDM16 (PR/SET domain 16)
Diseases named in the same sentence as PRDM16 in open-access papers (continued):
Sharing a sentence is not in itself a finding about the gene and the disease.
kidney diseases (1 paper, 2025). "Prdm16 knockout accelerated aging in multiple organs, including the kidneys, lungs, heart, and brain, and was associated with aging‐related kidney disease." (PMID 40946183, 2025). "We further investigated the role of PRDM16 in aging‐related kidney diseases, considering that the kidneys exhibited the highest expression level of PRDM16." (PMID 40946183, 2025). "Furthermore, tubular‐specific Prdm16 deletion aggravates irradiation‐induced kidney aging and aging‐related kidney diseases in irradiated mice subjected to ischemia‐reperfusion surgery." (PMID 40946183, 2025). "Tubular‐specific Prdm16 knockout aggravated aging‐related kidney disease." (PMID 40946183, 2025). "Taken together, these results show that the tubule‐specific Prdm16 deletion aggravates irradiation‐induced kidney aging and accelerates UIRI‐induced kidney disease under aging conditions." (PMID 40946183, 2025).
PRDM16 also shares sentences with these, for which no sentence is quoted: myelodysplastic syndrome (5 papers); left ventricular noncompaction (4); melanoma (4); Stroke (3); Cluster headache (2); gastric tumor (2); Hearing impairment (2); Hematologic cancer (2); Left ventricular noncompaction cardiomyopathy (2); osteosarcoma (2); rhabdoid tumor (2); acute lymphoblastic leukemia (1); arteriovenous malformations (1); atrial septal defect (1); autism (1); autonomic dysfunction (1); B-cell acute lymphoblastic leukemia (1); bacterial infection (1); bladder urothelial carcinoma (1); brain tumor (1); central nervous system disorder (1); chronic kidney disease (1); colon adenocarcinoma (1); colon cancer (1); colorectal cancer (1); dyslipidaemia (1); epilepsy (1); Erythema (1); esophageal squamous cell carcinoma (1); familial cardiomyopathy (1).
A further 31 diseases each share a sentence with PRDM16 in 1 paper.